TMEM67 (transmembrane protein 67)
Diseases named in the same sentence as TMEM67 in open-access papers (continued):
Sharing a sentence is not in itself a finding about the gene and the disease.
polycystic kidney disease (7 papers, 2013 to 2022). A usually autosomal dominant and less frequently autosomal recessive genetic disorder characterized by the presence of numerous cysts in the kidneys leading to end-stage renal failure. "We report two patients with a prenatal diagnosis of polycystic kidney disease with TMEM67 mutations identified in a whole-exome sequencing (WES) study." (PMID 34356094, 2021). "The same limitations are found in the Lewis polycystic kidney (LPK), Wistar polycystic kidney (Wpk) and Cy rat models, with mutations in the orthologs of human NEK8/NPHP9, TMEM67/NPHP11 and ANKS6/NPHP16 genes, respectively." (PMID 34055783, 2021). "The TMEM67 homozygous mutant rats have severe ventriculomegaly as well as severe polycystic kidney disease and die during the neonatal period." (PMID 30705305, 2019). "The TMEM67 homozygous rat is an orthologous model of MKS3 and demonstrates many of the characteristics of the human disease including severe polycystic kidney disease and brain abnormalities." (PMID 30705305, 2019).
COACH syndrome (6 papers, 2015 to 2022). "Here, we identified two novel compound heterozygous mutations (p.Gly132Ala and p.Tyr920ThrfsX40) in the TMEM67 gene in a 20-year-old male patient with COACH syndrome." (PMID 28860541, 2017). "Given the recessive nature of COACH syndrome, it stands to reason that TMEM67 mutations eliciting COACH syndrome are loss-of-function mutations." (PMID 28860541, 2017). "Mutations in the TMEM67 gene are responsible for the majority of COACH syndrome, with minor contributions from CC2D2A and RPGRIP1L." (PMID 26075130, 2015). "Mutations were identified throughout the TMEM67 gene in COACH syndrome patients." (PMID 28860541, 2017). "Thus, the presence of mutation in TMEM67 gene in this patient further delineates the genotype-phenotype correlation in COACH syndrome." (PMID 26075130, 2015). "We expected to find a higher rate of TMEM67 diagnoses than the three identified, given that TMEM67 is the leading cause of JBTS and MKS, and is also associated with NPHP and COACH syndrome." (PMID 35764379, 2022). "Second, Doherty and colleagues reported in COACH syndrome patients (UW52-3 and UW52-4) a mutation (p.Gly934GlyfsX26) in the G934 residue that is located in the C-terminal region of TMEM67, where the mutation we identified, p.Tyr920ThrfsX40, also resides." (PMID 28860541, 2017). "Our report of two novel mutations in TMEM67 will widen the genetic spectrum of COACH syndrome, thereby contributing to understanding the molecular pathogenesis of COACH syndrome." (PMID 28860541, 2017). "First, Gleeson, Valente and colleagues reported a COACH syndrome patient (COR71) who had p.Pro130Arg and p.Trp225* compound heterozygous mutations in TMEM67." (PMID 28860541, 2017). "Although mutations in TMEM67 (transmembrane protein 67)/MKS3 (Meckel-Gruber syndrome, type 3) were reported to cause COACH syndrome, this causality has not verified by functional studies." (PMID 28860541, 2017).
coloboma (5 papers, 2015 to 2022). An abnormality in which a part of a structure in one or both eyes is missing. "Hepatic disease, renal disease, ocular coloboma, and polydactyly are phenotypes observed in JS associated with TMEM67 mutations." (PMID 36468023, 2022). "Given the known association between TMEM67 mutations and coloboma, this additional feature is most likely explained by the causal gene mutations, while the additional NINL variant appears to have no obvious effect on the phenotype in individual UW57-3." (PMID 26485645, 2015). "The gene associated with the greatest number of patients with ocular colobomas is TMEM67." (PMID 35238134, 2022).
liver disease (5 papers, 2020 to 2023). "Our research group was the first to report a strong association between liver disease and the TMEM67 gene, detecting biallelic variants of TMEM67 in eight of 14 (57%) JS families with congenital liver fibrosis." (PMID 35238134, 2022). "In the NIH cohort, 21 of 22 patients (95%) with TMEM67 variants had evidence of liver disease, accounting for half of patients with this phenotype." (PMID 35238134, 2022). "The four patients with CEP290 gene mutations showed retinal degeneration, and the two patients with TMEM67 gene mutations had liver diseases." (PMID 33432080, 2021). "Thus, individuals with JS harboring causative variants in TMEM67 necessitate closer monitoring to allow early diagnosis and treatment of portal hypertension." (PMID 35238134, 2022). "Moreover, TMEM67-mutated patients with JS are also at increased risk for liver disease development complicated by probable portal hypertension in the second or third decades of life." (PMID 32000717, 2020). "The most relevant genotype-phenotype correlation has been established between TMEM67 sequence variations and the subtypes of JS with liver disease." (PMID 32000717, 2020). "Whereas phenotypes of the index patients with mutated PKHD1, TMEM67, and PPOX corresponded with those elsewhere reported, how F11R variation underlies liver disease remains unclear." (PMID 37471416, 2023). "The major phenotypes in our patients were consistent with those in previous reports indicating that the CEP290 mutation is correlated with retinal degeneration and kidney disease, TMEM67 is correlated with liver disease, and RPGRIP1L is correlated with kidney disease." (PMID 33432080, 2021).
nephronophthisis (5 papers, 2017 to 2024). Progressive tubulointerstitial injury, inherited in an autosomal recessive pattern, caused by mutations in genes involved in ciliary function, which may result in an end stage renal failure. "Therefore, it is possible that the phenotype in the affected lambs has a greater similarity to the phenotype observed in NPHP11 nephronophthisis patients, who have mutations in TMEM67, but lack occipital encephalocoele." (PMID 28487520, 2017).
Meckel Gruber syndrome type 3 (4 papers, 2013 to 2021). "Meckel-Gruber syndrome type 3 is an autosomal recessive genetic defect caused by mutations in TMEM67 gene." (PMID 24039893, 2013). "The compound heterozygous variants of TMEM67: c.637C > T (p.R213C) and TMEM67: c.579delA (p.G195Dfs*27) were identified and likely agreed with the Meckel Gruber syndrome type 3 (MKS3, MIM #607316), which segregated from the asymptomatic parents." (PMID 34032358, 2021).
nephronophthisis 11 (3 papers, 2013 to 2021). A nephronophthisis that has material basis in homozygous or compound heterozygous mutation in the TMEM67 gene on chromosome 8q22.1. "In the mimics group, 5 of 6 (83.3%) patients had kidney diseases, including nephronophthisis type 11 with homozygous TMEM67 gene mutation at 1843T>C 2012, Alport syndrome with monoalleic POLG1 mutation, unilateral renal agenesis, nephrolithiasis, and nonspecific chronic cardiac and renal failure." (PMID 34461951, 2021).
Obesity (3 papers, 2019 to 2025). Accumulation of substantial excess body fat. "While FOXP1 was found to be a common interaction partner of PP1MB, SFTPC and TMEM67, an intriguing finding was that the BLM gene was the only common gene among PCa, diabetes mellitus, and obesity, interacting with both FOXP1 and TMPO." (PMID 38235353, 2023).
RHYNS syndrome (3 papers, 2020 to 2023). RHYNS syndrome is characterized by the association of retinitis pigmentosa, hypopituitarism, nephronophthisis, and skeletal dysplasia. "Our findings extend the spectrum of phenotypes/syndromes resulting from biallelic TMEM67 variants to now eight distinguishable clinical conditions including RHYNS syndrome." (PMID 32928283, 2020).
Encephalocele (2 papers, 2019). A neural tube defect characterized by sac-like protrusions of the brain and the membranes that cover it through openings in the skull. "Based on the current findings, the TMEM67 homozygous rat is a good model of MKS as it demonstrates encephalocele-like changes, midline malformation and renal cystic disease." (PMID 30705305, 2019). "Although failure of cranial neural tube closure was described in a proportion of Tmem67 (MKS3) null mice, none of the mouse models appear to exhibit herniation of brain tissue outside the skull, which would represent an encephalocele." (PMID 31628096, 2019).
retinal degeneration (2 papers, 2021 to 2022). Degeneration of the retina. "In particular, patients presenting NPHP associated with retinal degeneration more often had causative variants in CEP290 and INPP5E, while those with NPHP but lacking retinal disease had molecular defects in CC2D2A, TMEM67, and NPHP1." (PMID 35238134, 2022).
Ventriculomegaly (2 papers, 2019 to 2020). An increase in size of the ventricular system of the brain. "Eight of eight (100%) of the heterozygous (TMEM67+/−) rats developed ventriculomegaly at age 8 months as compared to the age-matched WT (n = 10)." (PMID 30705305, 2019).
atrial septal defect (1 paper, 2015). Interauricular communication is a congenital malformation characterized by a communication between the atrial chambers of the heart. "Complex cardiac developmental defects, including ventricular septal defect, atrial septal defect and dextrocardia, were common malformations detected in Tmem67−/− embryos (n=6/8)." (PMID 26035863, 2015).
Bardet-Biedl syndrome type 20 (1 paper, 2024). "IFT172 variants have been associated with CH and Bardet-Biedl syndrome type 20, and TMEM67 variants have been associated with CH and Meckel/Joubert syndrome, and there is significant genetic overlap between these syndromes and Bardet-Biedl." (PMID 38822427, 2024).
cyst (1 paper, 2017). A sac-like closed membranous structure that may be empty or contain fluid or amorphous material. "In this model we have found mutations in TMEM67, dysmorphic primary cilia, and the presence of primary cilia fragments in cyst lumens." (PMID 28487520, 2017).
developmental delay (1 paper, 2021). "The four patients with CEP290 gene mutations had profound developmental delay, while the two patients with TMEM67 gene mutations had mild developmental delay." (PMID 33432080, 2021).
lung carcinoma (1 paper, 2022). "In PhenoScanner, 6 out of 12 hub genes (IRAK2, MECOM, ASB4, CDC42BPA, DPF3 and TMEM67) have revealed an association with lung related traits and lung cancer." (PMID 36194576, 2022). "Other COPD- hub genes (CDC42BPA, ASB4, DPF3 and TMEM67) are were also associated with lung function related traits and lung cancer." (PMID 36194576, 2022). "Additional COPD hub genes like SREK1, TMEM67, CDC42BPA, DPF3, and ASB4 were identified as prognostic markers in lung cancer, which is reported in 1% of COPD patients." (PMID 36194576, 2022). "Interestingly, we have also identified that the expression status of other COPD hub genes like SREK1, TMEM67, CDC42BPA, DPF3, and ASB4 improves the survival duration of lung cancer patients, hence they may act as potential molecular drug targets and/or biomarkers for both COPD and/or lung cancer." (PMID 36194576, 2022).
omphalocele (1 paper, 2015). Omphalocele is an embryopathy classified in the group of abdominal celosomias and is characterized by a large hernia of the abdominal wall, centered on the umbilical cord, in which the protruding viscera are protected by a sac. "Limb dysplasia, omphalocele and intrauterine growth retardation were detected in 20% (n=4/20) of Tmem67−/− embryos." (PMID 26035863, 2015).
prostate carcinoma (1 paper, 2021). A carcinoma that arises from epithelial cells of the prostate gland. "Elevated cellular levels of TACC3 were shown to induce loss of primary cilia through Aurora A induction and disruption of the transmembrane protein 67 (TMEM67)-filamin A complex, and promoted oncogenic transformation and shortened survival of the patients with prostate cancer." (PMID 34207779, 2021).
Pulmonary hypoplasia (1 paper, 2015). "Pulmonary hypoplasia is a nearly consistent finding in Tmem67−/− embryos and pups." (PMID 26035863, 2015).
Retinal coloboma (1 paper, 2012). A notch or cleft of the retina or choroid, located vertically below the optic disc. "Patients diagnosed with MKS, and that have additional features of ductal plate malformation and/or retinal coloboma, should be tested for TMEM67 mutations since, in any case, MKS mutations are most frequent in this gene." (PMID 23351400, 2012).
ventricular septal defect (1 paper, 2015). The presence of a defect (opening) in the septum that separates the two ventricles of the heart. "The majority of mutant Tmem67−/− pups died at birth, and none lived beyond the second postnatal day (P1), most probably because of pulmonary hypoplasia and complex cardiac malformations that include ventricular septal defect (VSD)." (PMID 26035863, 2015).
kidney disease (8 papers, 2017 to 2024). "In this cohort, the gene most commonly observed to cause renal disease was CEP290, followed by TMEM67 and more rarely AHI1 (two with unilateral multicystic dysplastic kidney)." (PMID 35238134, 2022).
tumor (2 papers, 2017 to 2021). "The TMEM44 and TMEM67 were found to be significantly correlated with the tumor stage in EC." (PMID 33463006, 2021). "The expression levels of TMEM44, TMEM67, CBX3, and ELOVL3 in tumor tissue were higher than in normal tissue, which was consistent with the trend in EC." (PMID 33463006, 2021). "Finally, a bovine B-cell/ATL tumour pair had integration sites 17 and 13 kb from the same host gene, respectively (T15, ATL4_2, TMEM67), while an ovine B-cell/ATL tumour pair had their proviruses integrated within and 430 kb downstream of the same host gene, respectively (M395/ATL25_10, ELF2)." (PMID 28534499, 2017).
genetic diseases (1 paper, 2017). "Further understanding of the molecular function of TMEM67 would help to uncover the mechanism by which mutations in TMEM67 cause various genetic diseases." (PMID 28860541, 2017).
neurological disease (1 paper, 2017). "Four of these genes have already been implicated in a neurological disease (TMEM67, FGFR1, FRAS1 and EXOSC8), but most variants affect genes that have not previously been connected to human disease phenotypes." (PMID 27457812, 2017).
TMEM67 also shares sentences with these, for which no sentence is quoted: Bardet-Biedl syndrome (5 papers); Alport syndrome (2); Alström syndrome (2); Joubert syndrome type 6 (2); Meckel syndrome, type 1 (2); polydactyly (2); retinal disease (2); scoliosis (2); asthma (1); autosomal dominant polycystic kidney disease (1); autosomal recessive deafness (1); beta thalassemia (1); Cohen syndrome (1); communicating hydrocephalus (1); congenital nephrotic syndrome (1); diabetes mellitus (1); Fahr’s Disease (1); hearing loss (1); homocysteinemia (1); Kidney Cyst (1); Lowe syndrome (1); lung disease (1); Methylmalonic aciduria (1); MORM syndrome (1); nephrolithiasis (1); nutritional deficiency (1); occipital encephalocele (1); phenylketonuria (1); ptosis (1); renal agenesis (1).
A further 5 diseases each share a sentence with TMEM67 in 1 paper.